SOD2 (superoxide dismutase 2)
Diseases named in the same sentence as SOD2 in open-access papers (continued):
Sharing a sentence is not in itself a finding about the gene and the disease.
bladder cancer (continued). "Moreover, the relationship between the expression of SOD2 and overall survival time of prostate and bladder cancer was also investigated by Kaplan-Meier estimate." (PMID 31929112, 2020). "The association of SOD2 with aggressive metastatic cancer phenotype is further supported by positive correlation of increased SOD2 expression with consequent H2O2-related MMP9 and VEGF mRNA synthesis in bladder cancer." (PMID 29478325, 2019). "In bladder cancer, TRMP8 also regulates ROS production and the expression levels of the enzymes Catalase, HO-1, and SOD2, which regulate tumor growth in vivo, demonstrating that TRPM8 has an essential role in bladder cancer." (PMID 37033630, 2023). "BBM increased the intracellular ROS level by downregulating antioxidative genes such as Nrf2, HO-1, SOD2, and GPX-1 to suppress the progression of bladder cancer, while a novel synthetic BBM derivative, BBMD3, increased the production of ROS in osteosarcoma cells." (PMID 37382506, 2023). "However, the roles of SOD2, CDC42/Rac1, and JNK/c-Jun in bladder cancer aggression and migration remain largely unexplored." (PMID 25402510, 2015). "In conclusion, our study revealed that CAP could suppress proliferation and induce cell cycle arrest as well as ROS production possibly via FOXO3a-mediated pathways in bladder cancer cells, whereas no obvious cell apoptosis under the protection of increased catalase and SOD2 enzymes." (PMID 27775662, 2016).
colon carcinoma (24 papers, 2000 to 2025). "SOD3 is associated with inhibition of tumour growth and metastasis, while SOD1 and SOD2 are elevated in different stages of several cancers, including colon cancer, and can trigger proliferative and apoptotic signals depending on the amount of H2O2 produced." (PMID 36235125, 2022). "Moreover, downregulation of GDPD5 and SOD2 by these miRs or by small interfering RNAs also reverse EMT in colon cancer cell lines in vitro." (PMID 33429840, 2021). "The effect of Cd-O2/N2 atomized gas on the expression levels of NOX1, SOD2, and CAT in the colon tumors of the CC mice with intestinal stents implanted in them was not statistically significant." (PMID 38535948, 2024). "The injection of Cd-O2/N2 atomized gas further significantly suppressed the expression of SOD1 (C-Blank and C-Control: p < 0.001; C-S-Blank: p < 0.05), SOD2 (C-Control: p < 0.05), and CAT (C-Blank and C-Control: p < 0.01) in the colon tumors of the CC mice." (PMID 38535948, 2024). "Our data showed that droxinostat induced oxidative stress and ROS production in colon cancer cells, which is supported by the decreased expression of catalase, SOD1 and SOD2 with droxinostat treatment." (PMID 30065760, 2018). "When colon cancer cells were treated with fermentation supernatants derived from raw and roasted pistachios, they displayed increased caspase-3 activity, decreased H2O2-induced DNA damage, and increased CAT, SOD2, and GSTP1 gene expression mRNA levels." (PMID 40699792, 2025). "SIRT3 has been confirmed to enhance chemotherapy resistance of colon cancer by modulating the acetylation of superoxide dismutase 2 (SOD2) and peroxisome proliferator-activated receptor-gamma co-activator-1alpha (PGC-1α), which enabled SIRT3 to be an independent prognostic factor for colon cancer." (PMID 40421455, 2025). "The implantation of intestinal stents inhibited the expression of Superoxide Dismutase 1 (SOD1) in the colon tumors of the CC mice, with no evident effects on the expression levels of NOX1, SOD2, and Catalase (CAT) enzymes." (PMID 38535948, 2024).
myocardial infarction (24 papers, 2007 to 2025). Gross necrosis of the myocardium, as a result of interruption of the blood supply to the area, as in coronary thrombosis. "In conditions like myocardial ischemia or myocardial infarction, changes in SOD2 activity are closely associated with myocardial protection." (PMID 39458930, 2024). "The authors observed a decrease of Nrf2 protein levels in the left ventricle (LV) of a rat model of CHF following myocardial infarction (MI), with a consequent decrease of Nrf2-dependent antioxidant enzymes (HO-1, SOD2, and CAT) as well." (PMID 32575472, 2020). "Supporting this, a reduction in mitochondrial ROS through SOD2-targeted therapy improved oxidative phosphorylation and preserved endothelial resilience in non-reperfused myocardial infarction, highlighting MnSOD’s therapeutic potential in protecting coronary endothelium under ischemic conditions." (PMID 40722952, 2025).
Cerebral ischemia (23 papers, 2009 to 2025). Restriction of arterial blood supply to the brain associated with insufficient oxygenation to support the metabolic requirements of the tissue. "In this study, it was found that the increased expression of SOD2 is crucial to the injury and prognosis of cerebral ischemia reperfusion." (PMID 39109777, 2024). "The mitochondrial antioxidant enzyme superoxide dismutase 2 (SOD2) is the first-line defense against mitochondrial ROS release and, subsequently, reduces superoxide radicals and infarction volumes after cerebral ischemia." (PMID 36614118, 2022). "SOD2 and glutathione were critical for the cellular antioxidant defense in neurodegenerative diseases including cerebral ischemia." (PMID 34790286, 2021). "SOD2 knockout mice were more sensitive to oxidative stress after cerebral ischemia, while increased SOD2 alleviated ischemic brain injury." (PMID 30853891, 2019). "Using the Middle Cerebral Artery Occlusion (MCAO), we investigate whether SOD2 plays a neuroprotective role in cerebral ischemia." (PMID 39109777, 2024). "The results demonstrate that the enhanced neuroprotective effect of Feno after cerebral ischemia in transgenic mice may be related to the increased expression of SOD2." (PMID 39109777, 2024). "Similarly, the overexpression of SOD2 in transgenic mice produces neuroprotection from oxidative damage following transient focal cerebral ischemia and reperfusion." (PMID 37237948, 2023). "In cerebral ischemia, deacetylation of FoxO3a by SIRT3 causes the translocation of FoxO3a into the nucleus and enhancement of FoxO3a-dependent antioxidant protection associated with the activation of catalase and superoxide dismutase 2 (SOD2)." (PMID 35574497, 2022). "Our recent studies indicated that the PGC-1α–related pathway may enhance mitochondrial proteins UCP2 and superoxide dismutase 2 to counteract excessive reactive oxygen species (ROS) and increase mitochondrial biogenesis in the hippocampus after cerebral ischemia and experimental status epilepticus." (PMID 30823590, 2019). "On the other hand, it has been studied that ischemic brain damage after transient global or focal cerebral ischemia is significantly attenuated in transgenic mice and rats overexpressing SOD1 or SOD2." (PMID 30696078, 2019). "In addition, aconitase inactivation has been observed in various animal and cell models of neuronal disorders and oxidative stress including excitotoxicity, cerebral ischemia, beta-amyloid toxicity, oxygen-glucose deprivation, MPTP toxicity, Sod2 and DJ1 mutant mice as well as in aging." (PMID 19763183, 2009).
osteoporosis (23 papers, 2012 to 2025). A condition of reduced bone mass, with decreased cortical thickness and a decrease in the number and size of the trabeculae of cancellous bone (but normal chemical composition), resulting in increased fracture incidence. "Our findings not only elucidate the mechanisms by which an HFD induces BMSC senescence and associated osteoporosis but also offer new insights into treating HFD-induced osteoporosis by targeting the VDR-superoxide dismutase 2 (SOD2)-ROS axis." (PMID 38777841, 2024). "Contrary to rs5746094-G in SOD2, that was related to a protective association (OR = 0.23, p < 0.05; χ2 = 24.6206, p < 0.001) with osteoporosis." (PMID 37107290, 2023). "Polymorphisms of the SOD2 gene have an overwhelming effect on the occurrence of osteoporosis by virtue of manganese deficiency." (PMID 37834407, 2023). "Our findings also demonstrated that increased mitochondrial O2.− in osteocytes induced by Sod2 depletion causes typical age-related osteoporosis associated with reduced bone formation and increased bone resorption." (PMID 25779629, 2015). "For instance, SOD2 has been identified as the gene susceptible to osteoporosis in our previous integrative analysis of mRNA, SNP, and protein data." (PMID 25364766, 2014). "The expression of antioxidant-related proteins NRF2, HO-1, NQO1, FOXO1, and SOD-2 was increased to prevent advanced osteoporosis by inhibiting Aβ deposition and oxidative stress." (PMID 40153574, 2025). "ATG7 and superoxide dismutase 2 are involved in the pathogenesis of osteoporosis, and their expression levels correlated in osteoporotic mice and osteoporosis-free mice." (PMID 38553562, 2024). "It is likely that the SOD2 gene is also overexpressed and Mn is missing in Down syndrome, contributing to osteoporosis." (PMID 37834407, 2023). "Mice lacking osteocyte-specific mitochondrial superoxide dismutase 2 (SOD2) exhibit osteocytopenia and osteoporosis with increased ROS levels." (PMID 37198221, 2023). "While in terms of disuse osteoporosis, daphnetin up-regulated SOD2, eliminated ROS, restored SIRT3 expression and mitochondrial homeostasis in osteoclasts, resulting in inhibition of bone resorption." (PMID 36552574, 2022). "In summary, our study showed that melatonin ameliorates mitochondrial oxidative stress to improve bone mass around prostheses in osteoporosis via the SIRT3/SOD2 signaling pathway." (PMID 31110599, 2019). "The most significant gene SOD2 has been identified in our previous osteoporosis study involving the same expression dataset." (PMID 25364766, 2014). "Although both global knockout of cytoplasmic Sod1 as well as osteocyte-specific knockout of mitochondrial Sod2 seem to result in an osteoporosis-like phenotype in mice, several studies imply differences in the expression and the role of these antioxidative enzymes in bone." (PMID 35394023, 2022). "Another experiment showed that SIRT1 overexpression might enhance FOXO3a transcriptional activity by reducing its acetylation, increasing SOD2 expression, improving osteocyte antioxidant capacity, alleviating oxidative stress-induced bone damage, and countering osteoporosis." (PMID 40678144, 2025). "It has been demonstrated that circulating levels of catalase, superoxide dismutase 2 (SOD 2) and peroxiredoxin 2 (PRX2) are lower in postmenopausal women with osteoporosis than health controls." (PMID 35387349, 2022). "Our study proved that melatonin ameliorates mitochondrial oxidative stress in osteoporosis, promotes osteogenesis, and increases bone mass around prostheses via the SIRT3/SOD2 signaling pathway." (PMID 31110599, 2019). "It is also interesting that women with osteopenia had lower levels of catalase, SOD2, and PRX2 than those with osteoporosis." (PMID 31452599, 2019).
osteoporosis (continued). "Although decreased SOD2 activity and subsequent disbalance in mtROS have previously been described in aging mesenchymal progenitor cells, the consequences on bone integrity and development of osteoporosis have not been addressed before." (PMID 35394023, 2022).
depression (22 papers, 2015 to 2025). "In depressed subjects, the relative expression of microRNAs correlated positively with depression score, NO, iNOS, cortisol, and negatively associated with SOD2, CAT, and serotonin." (PMID 34721735, 2021). "Mitochondrial SOD polymorphism (SOD2) has been found to increase the risk of depression in the elderly." (PMID 34439504, 2021). "In older adults with depression, the expression levels of miR-124, miR-34a-5p, miR-135, and miR-451-a correlated positively with scores of depression, cellular nitric oxide (NO), iNOS, cortisol, and negatively associated with SOD2, CAT, and serotonin." (PMID 34721735, 2021). "The present investigation found a significant association between depression and self‐reported current psychological stress and the VV‐genotype of the Val16Ala‐SOD2 SNP." (PMID 31891227, 2020). "The results described in the present report, strongly suggest the association between Val16Ala‐SOD2 SNP and risk of depression and self‐reported psychological stress in elderly subjects, independent of other prevalent noncommunicable chronic diseases." (PMID 31891227, 2020). "However, the gene–gene analyses revealed that a risk of depression increased five-fold with genotypes such as T/T-T/T of SOD2 c.47T > C(p.Val16Ala)(rs4880) and NOS2 c.1823C > T(p.Ser608Leu)(rs2297518) polymorphisms (p = 0.013)." (PMID 32111088, 2020). "This selection could be relevant in the observation of a significant association between the SOD2 SNP and depression described in the present report." (PMID 31891227, 2020). "Therefore, the results described here regarding case‐control analysis strongly support the hypothesis that basal oxidative stress conditions associated with the SOD2 SNP may have some major influence on the risk of depression in the elderly." (PMID 31891227, 2020). "In our study, NOTCH3 was identified as a key factor in depression-induced GC progression by regulating SOD2 activity and influencing cellular oxidative stress levels." (PMID 40940884, 2025). "Specifically, in patients with pain-related TMD, the genotype AA of SOD2 polymorphism rs4880 was associated with higher hypervigilance scores, while the genotype CC of CAT SNP rs1001179 was associated with higher depression scores." (PMID 37371925, 2023). "Transcriptomic analysis of the human prefrontal cortex (datasets GSE54567 and GSE54568) revealed mitochondrial deacetylase sirtuin 3 (SIRT3) as the most significantly suppressed gene in depression (p < 0.01), suggesting an impairment in Superoxide dismutase 2 (SOD2)-mediated antioxidant defense." (PMID 41150784, 2025). "In addition, older adults with depression showed a significant increase (p =0.001) in the expression levels of mRNA of cellular iNOS gene with lower levels of the expressed mRNAs of SOD2 and CAT antioxidant genes, respectively, compared to that of healthy controls." (PMID 34721735, 2021). "However, studies correlating the Val16Ala‐SOD2 SNP with depression are still inconclusive." (PMID 31891227, 2020). "Likewise, decreased SOD2 mRNA and protein levels were found to be correlated with poorer memory, attention span, verbal fluency, and learning ability in a pooled sample of adults with recurrent depressive disorder and healthy controls." (PMID 27099827, 2016). "As it is well known that neuroinflammation and oxidative stress contribute parallelly to the etiology of depression symptoms, oxidative stress-related molecules were also measured, including NRF2, HO-1, SOD2, H2O2, and NO levels." (PMID 37978167, 2023). "Therefore, numerous polymorphisms, that occur within this gene [especially c.47C > T—SOD2 (rs4880)], play an essential role in the development mechanism of various diseases, including cancers (breast, prostate, bladder, and cervical cancers), depression, coronary artery disease, and type 1 diabetes." (PMID 35732787, 2022).
depression (continued). "Cellular nitric oxide (NO), and iNOS gene expression significantly increased and the expression levels of SOD2 and CAT antioxidant genes significantly decreased in older adults with depression." (PMID 34721735, 2021). "This study shows the effects of chronic administration of agomelatine on expression and the methylation status of Sod1, Sod2, Gpx1, Gpx4, Cat, Nos1, and Nos2 in the brain stricture and blood in the chronic mild stress (CMS) animal model of depression." (PMID 32545212, 2020). "Some polymorphs of manganese superoxide dismutase (MnSOD, SOD2) are more common in people with depression than in healthy people, which may lead to reduced MnSOD uptake by mitochondria and cause instability of this enzyme mRNA." (PMID 36768580, 2023). "The data showed that oxidative stress pramters; iNOS, SOD2, and CAT, and NO correlated positively with the changes in the domains of mood profile scores (depression, anger, fatigue, vigor, tension, TMSore), cortisol, and negatively with cellular serotonin levels." (PMID 34721735, 2021). "As a previous study reported that overexpression of Bmal1 can up-regulate the expression of Sirt3 and Sod2, and reduce mitochondrial dysfunction induced by 3-MCPD, in conjunction with our findings, we suspected that SIRT3 might also be involved in the development of depression modulated by Per3." (PMID 39894345, 2025).
glioblastoma (22 papers, 2001 to 2026). The most malignant astrocytic tumor (WHO grade IV). "Supportively in glioblastoma, the stemness featured subgroups with increased SOD2 that showed superior tolerance in oxidative stress, allowing them to take advantage in surviving cytotoxicity from another chemotherapy, temozolomide." (PMID 34681918, 2021). "SOD2 (Superoxide Dismutase 2) is highly upregulated in the mesenchymal subtype of glioblastoma." (PMID 41009025, 2025). "An increase in the mRNA expression of SOD2, GSR, and GPX4 was observed only in the MDR glioblastoma cell line, while CAT mRNA expression levels remained unchanged upon treatment with 2 and 5 in both cell lines." (PMID 41471777, 2025). "Moreover, CLO inhibits growth and inhibits genes related to OS defense (thioredoxin peroxidase, glutaredoxin, nitric oxide oxidoreductase, cytochrome c peroxidase and b5 reductase, GPx, SOD1, SOD2, and CAT) in glioblastoma patient biopsy-derived cell cultures." (PMID 41154163, 2025). "Temozolomide (TMZ)-resistant glioblastoma multiforme (GBM) cells exhibit mesenchymal and stemness traits and resist erastin-induced ferroptosis by activating the CYBB/NRF2/SOD2 pathway." (PMID 41601687, 2026). "Recent studies have shown that resveratrol induces the elevation of intracellular ROS by attenuating SOD2 and CAT expression and promoting the activity of caspase-9 and caspase-3, thereby remarkably arresting proliferation and triggering extensive apoptosis in glioblastoma multiforme (GBM) cells." (PMID 36558995, 2022). "Anti-oxidant genes such as CAT, SOD2, and GPX1 were not elevated in PAM- or PAL-treated glioblastoma cells." (PMID 31541175, 2019).
cognitive deficits (21 papers, 2012 to 2025). "Furthermore, the SOD2 and acetyl-SOD2 levels were associated with psychiatric symptoms and cognitive deficits." (PMID 40309794, 2025). "In an animal model of AD, HMGB1 induced cognitive impairment through the Sirtuin 3/superoxide dismutase 2 signaling pathway." (PMID 36906561, 2023). "Multiple sevoflurane exposures can cause brain damage and cognitive deficits in newborn mice, mediated via elevated levels of CHGB, PTEN, and MAP2c protein expression and reduced SOD2 expression." (PMID 36582614, 2022). "Knockout of SOD2 increased amyloid plaque burden and exacerbated cognitive deficits in mice, and conversely, SOD2 overexpression reduced oxidative markers, amyloid deposition, and cognitive deficit in transgenic AD mice." (PMID 32714148, 2020). "However, a large multi-site study investigating the impact of rs4880 on schizophrenia cognitive deficits, while measuring SOD2 activity, indicated that AA homozygotes had poorer attention performance." (PMID 38275640, 2023).